LRP1 (LDL receptor related protein 1)
Diseases named in the same sentence as LRP1 in open-access papers (continued):
Sharing a sentence is not in itself a finding about the gene and the disease.
cancer (continued). "In agreement with our data, low-density lipoprotein receptor-related protein-1 (LRP-1) and ApoE-binding receptors promote cancer cell migration via induction of MMP-2 and MMP-9 expression, and are involved in inducing cyclin D1 in interstitial fibroblasts." (PMID 31275318, 2019). "Several of the predicted targets are known to be involved in cancer progression (E2F1, E2F5, ERBB, PTEN), invasion and metastasis (ZEB1/2, LRP-1)." (PMID 30510566, 2018). "For example, genes with Motif 1 in Molecular Mechanisms of Cancer pathway include MAPK1, BRAF, SMAD2, FZD5, FZD8, NOTCH1 and LRP1, whereas genes with Motif 2 and/or Motif3 in the same pathway include LRP5, LRP6, MDM2, CTNND1, SMAD3, SMAD4 and SMAD7." (PMID 26040697, 2015). "SERPINE1, a secreted protein, promotes cancer invasion and metastasis via direct interactions with integrins, LRP1, uPA-uPAR with the ECM, and also correlates with a poor prognosis in most cancer types." (PMID 26335051, 2015). "We further demonstrated that the LRP-1-dependent regulation of MAPK signaling organizes the cytoskeletal architecture and mediates adhesive complex turnover in cancer cells." (PMID 20644732, 2010). "LRP1 was abundantly expressed in preadipocytes (3T3-F442A, 3T3-L1) and in fibroblasts (NIH-3T3, LRP1+/−MEFs, HMF), when compared to epithelial mammary immortalized (HMT3522-S1) or cancer (MCF7, MDA-MB231) cells." (PMID 19823686, 2009). "Notably, the co-chaperone of eHsp90, Morgana, which is secreted via unconventional pathways, enhances cancer cell motility via TLR2, TLR4, and LRP1 signaling." (PMID 41226319, 2025). "The top 20 up‐ and down‐regulated genes between malignant and mesothelial populations showed expected markers, such as PVRL4 or COL5A2, as well as genes that suggested a metabolically active cancer cell phenotype (WNT7B) and reactive mesothelial cells (MMP2 and LRP1) (upper heatmap)." (PMID 37691350, 2023). "Despite non-hypoxic growth conditions, certain cancer cell lines including brain, liver, and lung do still exhibit high levels of LRP1 expression, suggesting upregulation in tumors." (PMID 37020553, 2023). "It was previously confirmed that LRP1 is responsible for the invasion of cancer cells, but not in LRP1 silenced cells." (PMID 36839884, 2023). "Furthermore, LRP1 modulates the ERK and JNK pathways to regulate focal adhesion and cancer cell invasion." (PMID 37239055, 2023). "We speculated that LRP-1 is at the pivotal position to coordinate both the “eHsp90α > LRP-1” autocrine signalling and the EGFR signalling to support the constitutive motility of the cancer cells under serum-free conditions." (PMID 35835845, 2022). "We reported that LRP-1 functionalities in invasive cancer cells are not restricted to the endocytic control of extracellular matrix degrading enzymes." (PMID 36052226, 2022). "The gene encoding for a cytokine that can induce cell death in no-self cells and cancer cells is also up-regulated, together with LRP1, with which the former interacts, activating apoptotic cell death." (PMID 35954185, 2022). "LRP1 can act as a receptor for medium-term growth factors, signaling through ERK1/2 to induce the expression of internalized metalloproteinase, and promote the survival of micro-metastasis, thereby promoting cancer progression." (PMID 36030212, 2022).
cancer (continued). "Loss of ANXA6 has been reported to destabilize the ANXA6/low-density lipoprotein receptor-related protein 1 (LRP1)/thrombospondin-1 (TSP1) complex, which leads to reduced uptake of CAF-derived exosomes by cancer cells, and a reduction in their proliferative and migratory abilities." (PMID 32957712, 2020). "Because ERK serves as a key downstream mediator of LRP-1-regulated invasion and migration in cancer cells 35, we investigated whether PAI-1 induces PSC activation by triggering LRP-1/ERK signaling." (PMID 31695760, 2019). "Due to the abundance of CpG islands in LRP1 gene promoter and frequent hypermethylation of LRP1B, another member of the LRP family, in various cancer types, it could be possible that LRP1 gene methylation might regulate its expression." (PMID 29507659, 2018). "A recent report suggested that PAI-1 could also induce cancer invasion and metastasis by promoting EMT via interacting with integrin, LRP-1, uPA-uPAR, and the ECM, or via indirect classical signaling pathways." (PMID 27004408, 2016). "A lowering in LRP1 expression as observed in certain cancers (see supra) could thus result in CD44 accumulation at the cell surface and enforced cancer cell attachment." (PMID 26617523, 2015). "Here, we have used a network-based exploration approach to identify a multi-cancer gene expression biomarker highly connected by ESR1, PRKACA, LRP1, JUN and SMAD2 that can be predictive of clinical outcome in 12 types of cancer from The Cancer Genome Atlas (TCGA) repository." (PMID 26202601, 2015). "Although eHsp90-LRP1 regulated cytokines have not been well characterized, eHsp90 has been reported to signal through an LRP1-NF-kB pathway in cancer cells." (PMID 24805867, 2014). "In the cancer field, there is a notable lack of knowledge about intracellular signaling downstream of LRP-1 and understanding of its possible contribution to cancer progression." (PMID 20644732, 2010). "This retention mechanism of active kinases probably did not occur in our carcinoma model since we did not observe phosphorylated forms of JNK bound to LRP-1." (PMID 20644732, 2010). "In several cancers, including melanoma, lung cancer, and colorectal carcinoma, radiotherapy induces the release of PAI-1 into the circulation, which acts at distant sites to drive the differentiation of pericytes into SFRP2-high CAFs through the LRP1/p65 signaling pathway." (PMID 41008624, 2025). "Eight of the cancer types showed a significantly increased hazard ratio, while three of them significantly decreased hazard ratios with higher LRP1 expression, and others showed no significance and adversely affected disease-free survival (DFS) in KIPAN, GBMLGG, PAAD, and LGG." (PMID 39063239, 2024). "In colorectal cancer (CRC) cells, eHSP90α through LRP1, increases the levels of phosphorylated IκB kinase (IKK) α/β and NF-κB and induces the expression of TCF12, a class I member of the helix-loop-helix protein family preferentially overexpressed in CRC patients with cancer metastasis." (PMID 33544155, 2021). "Indeed, by inducing the endocytosis of DDR1, LRP-1 counteracts the negative effect of DDR1 on cancer cell proliferation." (PMID 32582700, 2020). "Thus, the expression of LRP1 on cancer cells cultured in ambient oxygen-rich conditions may not be an accurate reflection of its level of expression in cancer." (PMID 37020553, 2023). "Moreover, specific inhibitors of PKA significantly impaired calpain activity developed upon LRP-1 silencing and we could show by coimmunoprecipitation that the level of serine phosphorylation of calpain-2 was decreased by the PKA inhibitor H-89, specifically in LRP-1 expressing carcinoma cells." (PMID 36052226, 2022). "Macrophage inflammatory protein-1a/CCL3, known to amplify inflammation, is overproduced in the absence of LRP1 in myeloid cells, leading to enhanced CCR5-expressing monocyte recruitment to tumors and cancer angiogenesis." (PMID 32850302, 2020).
infection (31 papers, 2012 to 2025). The state of being infected such as from the introduction of a foreign agent such as serum, vaccine, antigenic substance or organism. "This was demonstrated by observing that OROV infection of Lrp1-deficient cells was significantly decreased." (PMID 41157652, 2025). "For these viruses, the reduced infection in LRP1-deficient cells was more or less maintained throughout the replication cycle." (PMID 37072184, 2023). "Previous studies have shown that mRAP can prevent infection by blocking Gn from associating with LRP1, thus producing a neutralizing effect." (PMID 37704627, 2023). "Indeed, increased proteolytic degradation was demonstrated for the cell surface associated low density lipoprotein related receptor 1 (LRP1) at late phase of infection." (PMID 26599541, 2015). "Additional RNA viruses also rely on LRP1 for later stages of infection, including the orthobunyavirus LACV." (PMID 41313001, 2025). "In this study, we explore the breadth of LRP1 usage by bunyaviruses and provide insights into the mechanism by which Peribunyaviridae use LRP1 for infection of neurons, a primary target of infection." (PMID 41313001, 2025). "The fact that LRP1 is highly conserved and is utilized in early infection of diverse bunyaviruses makes it an attractive target for the development of broad bunyavirus therapeutics." (PMID 41313001, 2025). "Domain 3 of mouse RAP protein (mRAPD3) can be added exogenously to cells prior to infection to interrogate reliance on LRP1 for infection, as we previously demonstrated with RVFV and OROV." (PMID 41313001, 2025). "In summary, we present evidence that LRP1 is a host factor involved in the early stages of cellular infection by JCV." (PMID 41313001, 2025). "Our data shown here provide evidence that LRP1 is needed for efficient early-stage cellular infection by JCV." (PMID 41313001, 2025). "One limitation of this study is that the effect of silencing LRP1 expression in Huh-7 cells was measured through virus yield in cell supernatant 24 h post-infection." (PMID 39599807, 2024). "For two of our tested viruses—namely VSV and especially SARS-CoV-2—LRP1 appeared to be only relevant for the later stages of infection." (PMID 37072184, 2023). "It is therefore possible that particle assembly and budding are the rate-limiting steps in RVFV infection, and dominate over the weaker impact that LRP1 has on the immediate–early infection phase." (PMID 37072184, 2023). "Plasma membrane–located low-density lipoprotein receptor–related protein 1 (LRP1 or CD91) is a host factor that supports the early infection stages of a spectrum of RNA viruses." (PMID 37072184, 2023). "Low-density lipoprotein receptor-related protein 1 (LRP-1) involved in cholesterol regulation was downregulated by infection, while LRP-1 inhibition increased intracellular cholesterol quantity and promoted DENV infection." (PMID 34899388, 2021). "Two different cell lines that stably overexpressed a specific shRNA for LRP-1 [shLRP-1(a) and shLRP-1(b)] were selected, and a control cell line was established after infection with control shRNA (shCTRL)." (PMID 32582700, 2020). "We found that an extracellular fragment of low-density lipoprotein receptor-related protein 1 (LRP-1) was present during infection." (PMID 31015516, 2019). "The current study identified extracellular fragments of Ae. aegypti LRP-1 that were only present during DENV2 infection." (PMID 31015516, 2019). "Human cytomegalovirus upregulates expression of host LDL receptor-related protein 1 early in infection, resulting in progeny virions that have reduced cholesterol and reduced infectivity." (PMID 29270154, 2017). "Down-regulation of LRP1 was nearly complete following infection with lentivirus carrying an shRNA against human LRP1 (lane 2 vs. lane 1)." (PMID 26846992, 2016).
infection (continued). "Since the cell viability started to decrease after infection with LRP1-shRNA for 4 days, LRP1-knockdown neurons were analyzed at day 4 of infection in all following experiments." (PMID 25500815, 2014). "Both neuronal and non-neuronal immortalized cell lines deficient for murine Lrp1 displayed reduced binding, internalization, and infection with JCV." (PMID 41313001, 2025). "The infection of DENV is also enhanced by down-regulating the expression of LRP1." (PMID 41244697, 2025). "To investigate whether the presence of LRP1 on the cell surface could impact the efficiency of infection, we examined the effect of shRNA-mediated LRP1 knock-down on viral yield." (PMID 39599807, 2024). "Thus, in line with the results from the acidic bypass experiment, this indicates that LRP1 plays a role in the immediate–early steps of RVFV infection, namely, cell attachment and entry." (PMID 37072184, 2023). "Moreover, using RVFV as a model, we observe that cholesterol acidification and endosomal acidification are involved in the positive influence of LRP1 on infection." (PMID 37072184, 2023). "Thus, taken together, our forward genetic screen in haploid mESCs enabled us to identify the cellular protein LRP1 as promoting infection by RVFV and some other RNA viruses including SARS-CoV-2." (PMID 37072184, 2023). "When the cells were given a surplus of cholesterol, infection was slightly reduced in LRP1-positive cells, but not in LRP1-negative cells, and also in this setting, the difference between LRP1-deficient and LRP1-sufficient cells disappeared." (PMID 37072184, 2023). "LRP1 restricts human cytomegalovirus infectivity by controlling the availability of cholesterol for the virion envelope, and increased LRP1 expression is likely a defense response to infection." (PMID 37168200, 2023). "The LRP1 expression is increased after Herpesviridae infection." (PMID 35997994, 2022). "Previous studies have shown animals lacking LRP1 are unable to develop adaptive immune responses following pathogenic infection." (PMID 35744696, 2022). "Thus, we identified LRP1 as a host factor that supports infection by a spectrum of RNA viruses." (PMID 37072184, 2023). "Primary hepatocytes were prepared from both mice three days after infection, and Western blotting and indirect immunofluorescence using an antibody against the 515 kDa LRP1 subunit demonstrated the efficient knock-down of LRP1 expression in hepatocytes isolated from AdCre-treated mice." (PMID 22238606, 2012). "In a heterologous competition experiment to further probe the role of Lrp1 in JCV infection, primary neurons were pre-treated with recombinant RVFV Gn followed by infection with JCV." (PMID 41313001, 2025). "Given the conserved use of LRP1 by distantly related bunyaviruses RVFV, SFTSV, and OROV, we interrogated the dependence on LRP1 for infection by JCV." (PMID 41313001, 2025). "The reduction in infection by JCV was visible by immunofluorescence microscopy, where both N2a and BV2 Lrp1 KO cells displayed decreased staining for JCV-N at 24 hpi compared to the WT cells." (PMID 41313001, 2025). "We pre-incubated human LRP1 CLII-Fc, CLIV-Fc, or an Fc control with 100–200 FFU of each indicated virus for 1 h prior to infection of Vero E6 cells." (PMID 41313001, 2025). "When Lrp1 KO BV2 cells were infected with JCV, OROV, or the virulent RVFV strain ZH501, we observed a reduction in infection when compared to the WT cells, confirming our previous findings." (PMID 41313001, 2025).
infection (continued). "GaPR-PCN exhibited excellent binding ability with host-derived heme-binding proteins (Hpx/LRP1 and Hpg/CD163) and the iron-regulated surface determinant (Isd) system of MRSA for infection site, infected cell, and intracellular targeting." (PMID 40963910, 2025). "Because LRP1 functions as an entry factor early in the infection process for both RVFV and OROV, we performed binding and internalization assays using BV2 cells to investigate if LRP1 is involved in the early stages of JCV infection." (PMID 41313001, 2025). "The Gn glycoprotein of the distantly related bunyavirus RVFV binds to CLII and CLIV of LRP1, and exogenous treatment of cells with recombinant RVFV Gn competitively inhibited both homologous infection with RVFV and heterologous infection by OROV." (PMID 41313001, 2025). "LRP1 promotes already RVFV particle attachment and internalization, and viral RNA levels in the mutant cells are lagging behind in the subsequent infection stages up to the 5-h p.i. time point." (PMID 37072184, 2023). "Inactivation of LRP1 in human cells reduced RVFV RNA levels already at the attachment and entry stages of infection." (PMID 37072184, 2023). "Our data suggest that the role of LRP1 in fostering RVFV infection is dependent both on cholesterol and on endocytosis early in infection." (PMID 37072184, 2023). "With the extension of infection, the levels of GPATC8 and TGF-β1 exhibited a gradual increase, whereas the level of LRP1 and AMY1 showed a gradual decrease." (PMID 36206314, 2022). "Furthermore, OROV and RVFV likely have overlapping binding sites on LRP1, as a soluble form of RVFV glycoprotein Gn is able to competitively inhibit OROV infection in vitro." (PMID 41313001, 2025). "A study showed that low-density lipoprotein receptor-related protein 1 (Lrp1) supports efficient cellular infection by OROV, although the mechanism is not fully explained." (PMID 41157652, 2025). "We observed that the levels of LRP1 expression in lambs clearly differed between organs but were not affected by the infection status." (PMID 37306574, 2023). "Western blot analysis revealed that infection of lentivirus carrying GluA1 plasmid significantly increased GluA1 levels both in control and LRP1-knockdown neurons without affecting LRP1 levels." (PMID 25500815, 2014). "Also, we showed that α2M*, a ligand of LRP1, directly binds DENV virions and favors DENV infection." (PMID 39599807, 2024). "However, as the levels of viral RNA are low at the attachment and entry stages of infection, we cannot rule out that for these viruses, the LRP1 effect is too small to be robustly detected at these early stages." (PMID 37072184, 2023). "Knock-down of LRP1 in sensory neurons during the acute infection step appeared to decrease uptake of PrPSc but had no influence on overall PrPSc levels four weeks post infection, a time point at which PrPSc replication is usually not observed in untreated sensory neurons." (PMID 23340381, 2013). "For EMCV, none of the replication stages was affected by a lack of LRP1, whereas VSV RNA levels were reduced at the 24-h p.i. time point of infection." (PMID 37072184, 2023). "The inhibition of acidification by bafilomycin A1 strongly impaired infection of the cells, whereas the endocytosis bypass did not substantially affect RVFV RNA levels, but wiped out the difference between the LRP1-positive and LRP1-negative cells." (PMID 37072184, 2023).